STAT3 (signal transducer and activator of transcription 3)
Diseases named in the same sentence as STAT3 in open-access papers (continued):
Sharing a sentence is not in itself a finding about the gene and the disease.
tumor (continued). "Indeed, at the bone metastatic site, IL-6 indirectly contributes to OC differentiation and activation by increasing RANKL expression in OB via the JAK/STAT-3 signaling pathway, thereby further promoting tumor local aggressiveness." (PMID 34124067, 2021). "Also, the STAT3 signaling pathway is the main intrinsic tumor inflammation pathway, because it is frequently activated in the malignant cells and regulates many tumor inflammatory genes in the tumor microenvironment." (PMID 34129726, 2021). "Based on the present data and previous reports, we propose that inhibition of the IL-6/STAT3 signalling pathway may promote the introduction of anti-tumour immunity into the tumour microenvironment." (PMID 34078370, 2021). "Meanwhile, GPRC5A, which can behave as an oncogene or tumor suppressor depending on context, was upregulated in CTBs with coincident downregulation of STAT3, suggesting that it may function as a tumor suppressor in this system." (PMID 34121116, 2021). "Importantly, Tris DBA downmodulated the expression of activated JAK1, JAK2, and STAT3, and Ki-67 in MM tumor tissues." (PMID 34771643, 2021). "Tumor-associated MDSCs promote tumor progression by inducing tumor angiogenesis via the release of growth factors, cytokines, and metalloproteinases (e.g., VEGF, Bv8, MMP9) in response to tumor hypoxia and by STAT3 activation in MDSCs." (PMID 34771577, 2021). "These pathogens activate tumor signaling pathways like NF-kB, STAT3." (PMID 33823861, 2021). "The in vivo quantitative proteomics labeling technique called stable isotope labeling in animal cell culture (SILAC) was employed to identify the proteins of interest between revertant vs parental cells, and reported the significance of STAT3 in tumor reversion." (PMID 33958005, 2021). "Since we previously determined that both TRAF2 and STAT3 are suppressed by miR-671-5p to affect tumor migration, CSC ability and radioresistance in GBM, we attempted to identify the clinical connection between TRAF2 and STAT3 expression and disease progression." (PMID 35052701, 2021). "In CRC patients, the tumor-associated NK cell (TANK) was found to make contributes to the tumor angiogenesis and invasion through secreting proangiogenic factors and tissue remodeling/invasion factors secretion via STAT3 and STAT5 pathway." (PMID 33262461, 2021). "Macrophages could increase the proliferation of HCC stem cells through the IL-6/STAT3 signaling pathway and then promote tumor growth." (PMID 34604045, 2021). "STAT3 plays a significant role in tumor angiogenesis by regulating VEGF activity." (PMID 33805840, 2021). "Finally, we assessed the levels of survivin (the downstream target oncogene in the ALK and STAT3 pathways) in tumor tissues." (PMID 33758275, 2021). "Therefore, compounds 2 and 5 played an anti-tumor role via inhibiting the expression of pro-oncogenic genes induced by activated STAT3." (PMID 34638708, 2021). "However, the role of STAT3 in CRC development remains controversial, as there are reports that show elevated STAT3 had tumor promoting activity and also tumor inhibitory effects." (PMID 33846436, 2021). "But it remains to be explored in the future whether STAT3 inhibitors act directly on Treg cells, which subsequently modulate the TME through tumor-associated antigens." (PMID 33936081, 2021). "For instance, elevated levels of IL-6 are produced due to a positive feedback mechanism in the tumor microenvironment, which may regulate the persistent phosphorylation of STAT3 signaling in human cancers." (PMID 34771643, 2021). "For example, Stat3 inhibitor was shown reductions in inflammation and tumor development, which may prompt us to the application of a similar strategy against inflammatory diseases where IL6 is overproduced, such as sepsis and EAE." (PMID 35126382, 2021).
tumor (continued). "This may be explained, in part, by the participation of tumor-secretory cytokines and chemokines that are inhibited by STAT3, which then promotes dendritic cell maturation and T cell activation." (PMID 34829795, 2021). "The activation of the IL-6/JAK/STAT3 signaling pathway can inhibit the function of immune cells in the tumor microenvironment, and inhibition of the IL-6/JAK/STAT3 signaling pathway can inhibit the growth of tumor cells and alleviate the immunosuppression in the tumor microenvironment." (PMID 34422050, 2021). "Moreover, IL-11 and IL-6 drive the malignant development of tumor cells by the activation of STAT3 as well as by the upregulation of angiogenic and inflammatory factors." (PMID 33917793, 2021). "Our results illustrated that ESR1 may act as a tumor suppressor by inhibiting the JAK/STAT3 signaling pathway." (PMID 33865377, 2021). "PS-acet.-STAT3 peptide effectively suppresses human HCT116 tumor growth." (PMID 33491667, 2021). "Our findings also supported STAT3 as a critical target for the anti-tumor activity of fraxetin." (PMID 34320467, 2021). "Indeed, the IL-6/STAT3 signaling pathway stimulates cell proliferation and migration/invasion, and protects tumor cells from drug-induced apoptosis." (PMID 34830463, 2021). "Moreover, diverse STAT3 inhibitors have already been shown to be effective by inducing the apoptosis of tumor cells." (PMID 33525658, 2021). "Additionally, the expression of STAT3 in tumor tissue serves as a predictive marker of prognosis, and elevated STAT3 expression is associated with a reduced prognostic ability and worse three-year overall survival rate of human solid tumors." (PMID 34771643, 2021). "Thus, it appears that colonic fibroblasts produced IL-11 in response to factors from tumor cells, which, in turn, activated and induced STAT3 phosphorylation in both IL-11+ and IL-11− colonic fibroblasts in an autocrine or paracrine manner." (PMID 33863879, 2021). "Several drugs already used in chemotherapy to suppress tumor growth, including sorafenib, dovitinib and the Mcl-1 inhibitor SC-2001, exert their antitumor effects by enhancing the phosphatase activity of Shp1 on the transcriptional factor STAT3." (PMID 34088320, 2021). "TAMs can also directly support chemoresistance by secreting insulin-like growth factors (IGF)-1 and -2 which activate insulin/IGF receptors on pancreatic cancer cells, as well as Resistin, which binds to CAP-1 and TLR-4 on tumor cells and promotes gemcitabine resistance via STAT3 signaling." (PMID 34201127, 2021). "Moreover, other targeted therapies such as proteasome inhibitors, histone deacetylase (HDAC) inhibitors (HDACi), and STAT3 inhibitors have been shown to sensitize tumor cells by increasing the level of ROS." (PMID 33920160, 2021). "We further assessed whether dimerized PS-acet.-STAT3 peptide can suppress tumor growth more effectively than its monomer counterpart in vivo." (PMID 33491667, 2021). "In addition, OSM-mediated induction mainly comes from the regulation of STAT3, and MES-like tumor cells are also associated with increased mesenchymal expression of macrophages and increased cytotoxicity of T cells." (PMID 34630121, 2021). "Similar to tumor cells, the tumor-infiltrating immune cells, such as TAMs, have been reported to present the constitutive activation of STAT3; thus, inhibition of STAT3 activation by resveratrol demonstrates a proof-of-principle that resveratrol can indeed inhibit TAMs in the tumor microenvironment." (PMID 33802331, 2021). "Therefore, the concept of reducing tumor aggressiveness by interfering with STAT3 hyperactivity seems intriguing." (PMID 34094963, 2021). "However, multiple signaling pathways converge in STAT3, leading to a critical role in tumor growth and resistance." (PMID 34059647, 2021).
tumor (continued). "In histopathologic examination, phosphorylated STAT3 preferentially localizes to tumor endothelial cells along with vascular endothelial growth factor receptor-2 (VEGFR-2), suggesting an autocrine feed-forward loop promoting the hallmark neovascularization seen in GBM." (PMID 33498872, 2021). "Moreover, we explored the role of STAT3/NF-κB pathway in the PAR1/PAR4 activation-induced tumor promoting/inhibitory effect." (PMID 34844621, 2021). "Persistent STAT3 activation has been reported in 30% to 100% of human PDAC tumor specimens." (PMID 33491667, 2021). "Similarly, IL-6/STAT3 signaling has been described in other tumors such as osteosarcoma, and targeting this axis has been proposed for ablating tumor-stroma crosstalk." (PMID 33287630, 2021). "It is known that the activation of STAT3 signaling in the cells of host tissues produces soluble factors which are able to repress both the migration and the recruitment of NK cells, e.g., into pro-inflammatory tumor sites." (PMID 34476533, 2021). "STAT3 is considered to be an oncogene and may regulate oncogenic events involved with cell‐cycle progression, apoptosis, tumour angiogenesis, invasion, metastasis and evasion of the immune system of OS." (PMID 33382511, 2021). "In addition, these factors will further promote the activation of STAT3 and form a paracrine or autocrine-dependent feedback loop, leading to a continuous increase of inflammation in the tumor microenvironment." (PMID 34702277, 2021). "shows that CXCL9 activated STAT3 signaling in CD8+ T cells of PDAC cell, and suppression of STAT3 could recover the proliferation and secretion of anti-tumor cytokines of CD8+ T cells." (PMID 34367961, 2021). "WB and IHC were employed to verify the SOCS3/JAK2/STAT3 expression in the tumor tissues of mice." (PMID 34388111, 2021). "STAT3 represents an attractive therapeutic target, because it coordinates the crosstalk between cancer cells and immune cells from the TM, thus regulating the anti-tumor immune response." (PMID 34440220, 2021). "Blocking JAK/STAT3 signaling with SOCS3 might activate antitumor immunity in the tumor microenvironment." (PMID 34830179, 2021). "Additionally, orlistat inhibited the extent of inflammation, hyperplasia, and tumor progression via the inhibition of STAT3 and NF-κB activation." (PMID 34440829, 2021). "In addition, CADM1 binds HER2 through its extracellular domain and activates HER2 as well as CADM1 inhibited, which enhances tumor metastasis by activating the downstream STAT3 signaling pathway." (PMID 34395444, 2021). "STAT3 is constitutively activated by phosphorylation of tyrosine 705 (Y705) in many cancers, acting as a point of convergence for oncogenic signaling pathways and promoting tumor cell survival and metastasis." (PMID 34067416, 2021). "Thus, STAT3 activation drives immune cells towards immunosuppressive phenotype by inhibiting regulatory T-cells, which in turn sustains tumor immune evasion." (PMID 34138876, 2021). "In tumor cells, an increase in the lysine acetylation of the STAT3 induces cell growth." (PMID 34488773, 2021). "To test this hypothesis, we constructed a novel IL20RA-targeted liposomal NP carrying the STAT3 inhibitor stattic (NP-Stattic-IL20RA) to target IL20RA+ tumor cells." (PMID 33456560, 2021). "Tumor-derived exosomes were also reported to induce MDSCs through STAT-3 dependent manner." (PMID 34078376, 2021). "BD treatment may induce ANXA2, TGFI, FN1, HSP90B1 down-regulation, and FRK up-regulation to inhibit tumor metastasis by regulating autophagy, hypoxia, β-catenin, and STAT3 signaling pathways." (PMID 34685653, 2021). "In tumor cells, the constitutive activation of STAT3 suppresses the antitumor immune response by inhibiting the expression of Th1 mediators and inducing the production of multiple immunosuppressive factors, leading to tumor immune evasion and tumor progression." (PMID 34943817, 2021).
tumor (continued). "In the context of IL-15 immunotherapy, pharmacological targeting of STAT3 may thus be preferably only some time following the localization and priming-enhanced adaption of NK cells to hypoxic sites such as the tumor microenvironment." (PMID 33782423, 2021). "Both phosphorylated STAT3 (activated) and NF-κB levels have been reported to be high in tumor-initiating cells, a subpopulation within the bulk tumor with “stem-like” characteristics." (PMID 32797354, 2021). "STAT3 is multipotent regulator of both tumor cells and immune cells." (PMID 33957948, 2021). "STAT3 signaling is well studied as a significant intrinsic pathway for cancer inflammation due to its frequent activation in cancer cells that promotes inflammatory genes and suppresses anti-tumor immunity." (PMID 34887764, 2021). "Nevertheless, the PFS interval was better among PS with TNFR2 or STAT3 weak expression tumours." (PMID 33809542, 2021). "Aberrant STAT3 activation is mainly attributed to the excessive production of cytokines and growth factors in the tumor microenvironment (TM), high expression of protein tyrosine kinases, and epigenetic suppression of negative regulators of STAT3, such as SOCS3 and protein tyrosine phosphatases." (PMID 34440220, 2021). "After being released, it can bind with its specific receptor, namely CCR8, on peripheral Tregs and attract them to tumor sites where it induces a STAT3-dependent elevation of granzyme B level that would confer Tregs with a powerful weapon against their targets." (PMID 33868318, 2021). "Tumor cells reduce STAT3 signaling, downregulate hexokinase 2, and reduce glycolysis." (PMID 34771503, 2021). "This tumor reduction was associated with decreased levels of pro-proliferative ERK1/2-AP1 pathway and decreased activation of signal transducer and activator of transcription 3 (Stat3)." (PMID 33923030, 2021). "However, efferocytosis of tumor cells initiates NF-κB and signal transducer and activator of transcription 3 (STAT3) signaling, thus activating proinflammatory cytokine production, especially CXCL5." (PMID 34064859, 2021). "IL-6 directly acted on tumor cells and induced the increasing expression of STAT3 target genes." (PMID 34712264, 2021). "Thus, several studies have shown that IL-6, and downstream STAT3 signaling, is a critical tumor-promoting cytokine in CAC." (PMID 34884543, 2021). "Interestingly, we observed that GBM-N019 synergized with palbociclib and significantly delayed tumor growth with concomitant suppression of p-mTOR, mTORC1, mTORC2, Akt, NF-κB, STAT3, and CDK6 when compared to individual therapies." (PMID 34572040, 2021). "Studies also identified that the combination of cucurbitacins and anticancer agents can promote a synergism and may augment the chemotherapeutic effects via suppression of STAT3, being promising for tumor treatment." (PMID 33525658, 2021). "More importantly, targeting STAT3 has exhibited potent anti-tumor potential." (PMID 34025420, 2021). "Furthermore, it was reported that STAT3 can work as a tumor suppressor by inhibiting aerobic glycolysis of tumor cells, which decreases glucose consumption, lactate production, and expression of HIF-1α target genes in the tumor cells." (PMID 34692527, 2021). "AP-1 factors and STAT3 are particularly important for transformation in our model, and loss of ETS, KLF/SP1, THAP11, CREB, ZBTB33, or CEBP inhibits transformation or tumor growth in other cellular or animal models." (PMID 33523865, 2021). "The IL-6/STAT3 signaling pathway regulates tumor cell proliferation." (PMID 34771727, 2021). "M1 proinflammatory macrophages foster a pro tumorigenic environment by producing tumor-promoting cytokines, which exert a well-known proliferative effect on colonic cells via induction of transcription factor NF-κB and signal transducer STAT3." (PMID 34884543, 2021). "Active STAT3 in tumor cells contributes to the preservation of tumor cells by inhibiting apoptosis." (PMID 34488773, 2021).
tumor (continued). "Recently, JAK antagonist pacritinib, when used in combination with TMZ, elicited GSC-specific cytotoxicity and chemo-sensitization via regulating the JAK2/STAT3 axis in human GBM tumor initiating cells implanted in mouse brains, which eventually improved survival." (PMID 34439380, 2021). "In addition to supporting tumor cell proliferation, STAT3 activity is related to a variety of immunosuppressive mechanisms and is a key regulator of immune processes." (PMID 35047999, 2021). "The STAT3 pathway has been an important link between tumour and immune cells." (PMID 33605033, 2021). "STAT3 is abnormally activated in MDSCs in the tumor microenvironment." (PMID 33717204, 2021). "Studies have identified PEC as a STAT3 inhibitor to suppress tumor growth and metastasis." (PMID 35153751, 2021). "ITG2 activates upregulate STAT3 signaling pathway, which resulted in tumor progression." (PMID 34262595, 2021). "STAT3 signaling pathway is an indispensable loop in the tumor development promoted by MDSCs." (PMID 34527668, 2021). "The CXCL5/CXCR2 axis could activate multiple downstream signaling pathways, including PI3K/AKT, ERK1/2, and STAT3 to promote tumor progression in cancers." (PMID 33458757, 2021). "Furthermore, utilizing a mouse lung cancer xenograft model, this study showed that resveratrol significantly inhibited lung tumor growth, which was associated with the inhibition of cell proliferation and decreased expression of p-STAT3 in tumor tissues." (PMID 33802331, 2021). "Additionally, the results showing that AMG386 reduces p‐ERK1/2 and activates STAT3 in tumor endothelial cells are consistent with the reduced activity of EphrinB in tumor endothelial cells of mice treated with AMG386." (PMID 34102002, 2021). "Moreover, CD109 has been shown to be overexpressed in many neoplasms, including brain tumors, and to promote lung cancer metastasis via the STAT3 activity." (PMID 33986188, 2021). "Supporting the oncogenic effects of STAT3 in ES, it has been shown that STAT3 affects the surrounding tumor microenvironment through chemokine regulation and generally reduces tumor viability in ES cell lines when inhibited, as investigated by cell viability growth assays." (PMID 34440137, 2021). "In sharp contrast to the more widely accepted view that STAT3 promotes tumor progression, there are also reports that this transcription factor may serve as a tumor suppressor that facilitates differentiation and an epithelial identity of cancer cells." (PMID 34491463, 2021). "We speculate that RBM8A plays an indirect role in tumor immunotherapy by targeting STAT3 to enhance the tumor immune response." (PMID 34326876, 2021). "Besides, the expression of miR-106a-5p was increased but the expression of STAT3 was decreased by the circRHOT1 depletion in the tumor tissues of the mice." (PMID 33686957, 2021). "In summary, as the target gene of miR-370-3p, STAT3 may be a potential tumor promotor, which was regulated by circUBE2Q2." (PMID 34611143, 2021). "Among these pathways, JAK/STAT3 plays a classic role in promoting tumor invasion and metastasis." (PMID 34422809, 2021). "Meanwhile, the gene IL6R expression showed a positive correlation with tumor‐infiltrating lymphocytes in HSIL, solidifying the activation of the JAK/STAT3 signaling pathway contributing to inflammation occurring in the very early stage and promoting the neoplasia." (PMID 33694292, 2021). "Notably, blocking IL-6 with a neutralizing IL-6 receptor antibody effectively attenuated tumor burden and STAT3 hyperactivation in Apcmin/+Ripk3-/- mice." (PMID 33996591, 2021). "While it is clear that STAT3 activity supports tumor promoting “fibroblast-like” activity, it remains to be reconciled whether the cells assayed in studies thus far are purely reflective of CAFs." (PMID 34858425, 2021).